SLC49A4 (solute carrier family 49 member 4)
Description:
Mediates H(+)-dependent pyridoxine transport.
Synonyms: DIRC2; FLJ14784; RCC4
Tractability: Antibody: UniProt predicts a signal peptide or a membrane-spanning region. PROTAC: ubiquitination databases record sites on it.
Gene: Protein-coding gene on chromosome 3 (122,795,069 to 122,881,139, forward strand). Ensembl gene ENSG00000138463.
Subcellular location: Lysosome membrane
Subcellular location (Human Protein Atlas): Vesicles
Gene Ontology:
Molecular function: transmembrane transporter activity
Biological process: pyridoxine transport; transmembrane transport
Cellular component: lysosomal membrane; membrane
Genetic constraint (gnomAD): Loss-of-function variants: 27 observed, 39.59 expected, observed/expected ratio (o/e) 0.68, 90% interval 0.5 to 0.94. The upper end of that interval is the gene's LOEUF score, 0.94, which puts it in group 3 of 6, group 1 being the genes least tolerant of losing a copy. Missense variants: 436 observed, 495.57 expected, observed/expected ratio (o/e) 0.88, 90% interval 0.81 to 0.95. Synonymous variants: 220 observed, 198.48 expected, observed/expected ratio (o/e) 1.11, 90% interval 0.99 to 1.24.
Homologues: Orthologues: chimpanzee SLC49A4 (99% identical), macaque SLC49A4 (99% identical), rabbit SLC49A4 (96% identical), guinea pig SLC49A4 (95% identical), mouse Slc49a4 (95% identical), rat Slc49a4 (94% identical), dog SLC49A4 (94% identical), pig SLC49A4 (89% identical), tropical clawed frog slc49a4 (76% identical), zebrafish slc49a4 (69% identical). Paralogues in human: FLVCR2 (26% identical), FLVCR1 (25% identical), SLC49A3 (24% identical), CFAP276 (6% identical).
Diseases named in the same sentence as SLC49A4 in open-access papers:
SLC49A4 is named in the same sentence as 15 diseases in open-access papers, as found by Europe PMC text mining. Sharing a sentence is not in itself a finding about the gene and the disease. The quoted sentences say what the papers report.
cancer (11 papers, 2014 to 2025). A tumor composed of atypical neoplastic, often pleomorphic cells that invade other tissues. "A few cancers or cancer-related genes [such as EPHA1 (OMIM*179610), MGLL (OMIM*609699), DLG1 (OMIM*601014), SLC49A4 (OMIM *602773)] have also been observed." (PMID 38540211, 2024).
SLC49A4 also shares sentences with these, for which no sentence is quoted: renal carcinoma (13 papers); tumor (7); renal cell carcinoma (5); clear cell renal cell carcinoma (2); hepatocellular carcinoma (2); hereditary renal carcinomas (2); kidney cancer (2); breast carcinoma (1); cervical cancer (1); clear cell adenocarcinoma (1); glioma (1); neuroblastoma (1); Niemann-Pick disease, type C1 (1); pancreatic cancer (1).